MLPH (melanophilin)
Diseases named in the same sentence as MLPH in open-access papers (continued):
Sharing a sentence is not in itself a finding about the gene and the disease.
tumor (13 papers, 2016 to 2025). "Our data showed that during Gln deficiency, MLPH was upregulated in PDAC to promote tumor metastasis, suggesting a novel function of MLPH in facilitating metastasis." (PMID 39820281, 2025). "By considering the predisposing clinicopathological factors, our study observed that MLPH overexpression is associated with advanced tumor status, poor response to chemoradiation, and worse survival." (PMID 34829479, 2021). "Our results indicate that high levels of MLPH expression are associated with significantly aggressive tumor behavior, poor response to chemoradiation, and shorter survival." (PMID 34829479, 2021). "We found significant associations suggesting that decreased expression of MLPH in normal and tumor prostate tissue increases risk for PrCa (e.g., GTEx prostate MLPH ZTWAS = −5.80; PTWAS = 6.69 × 10−9; TCGA prostate ZTWAS = −6.77; PTWAS = 1.25 × 10−11)." (PMID 30287866, 2018). "Higher melanophilin level in prostate tissue of patients with a favorable PCa risk profile points out a tumor‐suppressive effect." (PMID 26411452, 2016). "Taken together, the expression pattern of MLPH points toward a tumor‐suppressive function of MLPH, which is weakened in the presence of a rs11891426:T>G risk G allele by attenuation of androgen and AR‐regulated expression of MLPH." (PMID 26411452, 2016). "Higher expression of MLPH in the prostate tissue of cancer patients with a favorable risk profile provides evidence for a tumor‐suppressive function of this protein." (PMID 26411452, 2016). "Therefore, we were able to comprehensively observe the association between MLPH expression and early-/advanced-stage groups and their tumor regression grade." (PMID 34829479, 2021). "MLPH knockdown inhibited tumor growth compared to the NC group, the volume and weight of the tumor confirmed this equally." (PMID 39308678, 2024). "On the contrary, MLPH overexpression promoted tumor growth compared to the Vector group, and it is also consistent with tumor volume and weight measurements." (PMID 39308678, 2024). "Compared with the normal group, the tumor group had higher expressions of MLPH, MISP, KDM6B, and FXYD3 genes." (PMID 35673567, 2022). "Subsequently, the correlations between MLPH expression and clinicopathologic features, tumor regression grade, disease-specific survival (DSS), local recurrence-free survival (LRFS), and metastasis-free survival (MeFS) were analyzed." (PMID 34829479, 2021). "In order to correlate the expression of MLPH with the distinct SNP allele, MLPH immunohistochemistry analysis was carried out employing a TMA containing benign and tumor tissue cores of radical prostatectomy specimens obtained from 68 patients." (PMID 26411452, 2016). "A similar expression pattern of MLPH was also found for the rs2292884:A>G SNP (P = 0.0084 in benign, P = 0.058 in tumor tissue)." (PMID 26411452, 2016). "Notably, analysis of clinical samples from the National Cheng Kung University Hospital (NCKUH) using the Tumor-Node-Metastasis (TNM) staging system revealed that patients with PDAC with higher MLPH expression showed poorer prognosis." (PMID 39820281, 2025). "Through assay for transposase-accessible chromatin using sequencing (ATAC-seq), we detected increased chromatin openness of squamous markers (TP63, KRT5, KRT6A and KRT14) and reduced chromatin accessibility of adenomatous markers (KRT7 and MLPH) in the DR tumor cells." (PMID 39687207, 2024). "MLPH depletion did not affect the size of the 3D tumor spheroids; however, the proportions of invading spheroids were increased in -QQ groups, and depletion of MLPH reduced the phenotype." (PMID 39820281, 2025). "For example, FOXA1, MLPH, NAT1, MAPT and BAG1 are expressed in luminal tumours according to published mRNA profiles and also co-clustered in our data, with higher expression levels in most ERPR tumours." (PMID 26725330, 2016).
cancer (11 papers, 2014 to 2025). A tumor composed of atypical neoplastic, often pleomorphic cells that invade other tissues. "Second, MLPH also acts as an effector protein for Rab27, which has long been implicated in the progression of various cancers." (PMID 34829479, 2021). "Collectively, MLPH overexpression is strongly associated with tumorigenesis and poor cancer outcomes; however, the link between MLPH and cancer metastasis remains unclear." (PMID 39820281, 2025). "In this study, differential MLPH expression in cancer tissues and the adjacent tissues was evaluated using the Gene Expression Profiling Interaction Analysis 2 (GEPIA 2) and Human Protein Atlas (HPA) databases." (PMID 39308678, 2024). "Although some cancer genes have also been reported to be under recent positive selection, such as the prostate cancer-related gene MLPH, systematic investigation of the role of recent selection on the adaptive evolution of cancer genes remains sparse." (PMID 37098512, 2023). "The protein biomarkers identified, such as CK7, CDH17, MLPH, FABP1, and NARR, can be used for differential diagnosis between the two cancers in primary healthcare institutions using IHC staining." (PMID 38608841, 2024). "Knocking out C9orf89, MAGI2, MLPH, or RHBDD2 in supporting cells reduced the ratio of apoptosis of cancer cells." (PMID 37264057, 2023). "At the present time, the precise functions of ACSL5, MLPH and TMEM45B in cancer remain unknown." (PMID 24625834, 2014).
metabolic disease (1 paper, 2023). A congenital disorder (due to inherited enzyme abnormality) or acquired (due to failure of a metabolically important organ) disorder resulting from an abnormal metabolic process. "In this family, we investigated the role of a new hypomorphic RAB27A variant, on a metabolic disease background, for its pigment distribution in melanocytes, binding to its interaction partners MLPH/SLAC2-A, SLP2-A and MUNC13-4 and its impact on cytotoxic function of NK and T cells." (PMID 37388727, 2023).
MLPH also shares sentences with these, for which no sentence is quoted: hemophagocytic lymphohistiocytosis (2 papers); adenocarcinoma (1); bladder cancer (1); essential hypertension (1); Hepatoma (1); Hermansky-Pudlak syndrome (1); Hydrocephalus (1); Hypertension (1); Immunodeficiency (1); leukemia (1); Menkes syndrome (1); metastatic tumors (1); ocular albinism type 1 (1); oculocutaneous albinism type 1 (1); pancreatic ductal carcinoma (1); pneumoconiosis (1); prostate adenocarcinoma (1); pulmonary fibrosis (1); rectal tumors (1); skin melanoma (1); squamous cell carcinoma (1); thyroid cancer (1); uterine sarcoma (1); vitiligo (1).